GCG (glucagon)
Diseases named in the same sentence as GCG in open-access papers (continued):
Sharing a sentence is not in itself a finding about the gene and the disease.
diabetes (continued). "Insulin therapy, which normalizes blood glucose without affecting the open KATP channel, prevented the changes in insulin- and glucagon-staining, β-cell ultrastructure and number of ins+/glu+ cells produced by 4 weeks of diabetes." (PMID 25145789, 2014). "These authors reported that accelerated proteolysis of uncontrolled diabetes occurs as a result of deranged glucagon-mediated regulation of cyclic AMP formation in insulin deficiency." (PMID 23861717, 2013). "In this section the researchers introduce the demographic data, general knowledge about diabetes, general knowledge of insulin and glucagon use, general knowledge of complications, general knowledge of diabetic diet and general knowledge of physical exercise." (PMID 24171891, 2013). "Accordingly, immunoneutralization of glucagon or genetic deletion of the glucagon receptor improved glucose homeostasis in animal models of diabetes." (PMID 23744070, 2013). "In conclusion, the existing data clearly show that melatonin has a stimulatory effect on glucagon secretion in pancreatic α-cells and on hepatic glucagon action in the liver, and indicate disturbances of these effects in diabetes." (PMID 23535335, 2013). "Diabetes is a bihormonal disorder involving both inadequate insulin secretion and defective glucagon secretion." (PMID 24315372, 2013). "The percentage of diabetes-related costs for injection needles/syringes, glucagon sets, and other medication amounted to each at most 2% of total costs." (PMID 23967077, 2013). "Oral administration of BCM7 for 30 days to rats with STZ-induced diabetes resulted in a significant increase in serum level of insulin, and a decrease in the level of glucagon." (PMID 23658831, 2013). "Automated closed-loop control of blood glucose concentration is a daily challenge for type 1 diabetes mellitus, where insulin and glucagon are two critical hormones for glucose regulation." (PMID 24260042, 2013). "On the other hand, some researchers think that atypical ketosis-prone diabetes is a subtype of type 2 diabetes that develops in patients with high sensitivity to glucotoxicity or lipotoxicity or with dysregulated glucagon secretion." (PMID 23324539, 2013). "Selective inhibition of PC2 is a strategy to regulate glucagon production towards the management of diabetes." (PMID 23451118, 2013). "The role of glucagon in the pathophysiology of experimentally induced type 1 diabetes mellitus (T1DM) was also recently reported by Unger and colleagues." (PMID 23744070, 2013). "This review integrates the physiology of glucagon secretion regulating glucose homeostasis in vivo to single α-cell signaling, and how both become perturbed in diabetes." (PMID 22969729, 2012). "This is a considerable challenge in insulin therapy as failure of glucagon counterregulation during hypoglycemia is a key factor limiting insulin treatment in patients with diabetes." (PMID 23316165, 2012). "The forced expression of Pax4 in glucagon-expressing alpha-cells is able to convert these into functional beta-cells that counter chemically induced diabetes in mice." (PMID 23326678, 2012). "In diabetes, however, while insulin secretion or action is insufficient, the production and secretion of glucagon are excessive, contributing to the development of diabetic hyperglycemia." (PMID 23316165, 2012). "Remarkably, the sole misexpression of Pax4 in glucagon-expressing cells is able to induce their regeneration, endow these with beta-cell features, and thereby counter chemically induced diabetes." (PMID 22717987, 2012). "In contrast to dogs, in totally depancreatized humans, there is only a negligible amount of plasma glucagon, and in contrast to depancreatized dogs, in depancreatized humans, diabetes is very mild." (PMID 22969729, 2012).
diabetes (continued). "It is well known that the release of glucagon by the pancreas is inhibited by both insulin and somatostatin; and in diabetes, defects in the release of these islet paracrine hormones contribute to the perturbation of glucagon release from α-cells." (PMID 22969729, 2012). "Dysregulation of glucagon has received less attention in this regard, but is also thought to play an important role in diabetes." (PMID 23185367, 2012). "Along the same line of evidence, the sole forced expression of Pax4 in glucagon-producing cells is able to reprogram alpha-cells into functional beta-cells that can counter chemically induced diabetes." (PMID 23326678, 2012). "We then discuss the complex crosstalk between the islet cells and the breakdown of this crosstalk in diabetes contributing to the dysregulated glucagon secretion." (PMID 22969729, 2012). "In summary, our study has revealed that glucagon-producing α-cells and somatostatin-producing δ-cells can rapidly regenerate following a single diabetes-inducing dose of STZ treatment in adult mice." (PMID 22586489, 2012). "In patients with diabetes, pancreatic α-cells fail to secrete glucagon in response to low blood glucose." (PMID 22716962, 2012). "Remarkably, the forced expression of Pax4 in glucagon+ cells in vivo was found to induce their regeneration and subsequent conversion into functional beta-like cells that can counter chemically-induced diabetes." (PMID 22717987, 2012). "In treatment of diabetes aimed at rigorously reducing hyperglycemia to avoid chronic complications, the resulting hypoglycemia triggering glucagon release from α-cells is frequently impaired, with ensuing hypoglycemic complications." (PMID 22969729, 2012). "To date, the dysfunction of glucagon secretion in diabetes is vaguely considered to result from defective glucose sensing and insulin resistance in liver and muscle." (PMID 21283589, 2011). "Given that IDE is known to degrade other substrates involved in glucose homeostasis and diabetes pathogenesis, including glucagon and amylin, this question merits further investigation." (PMID 21695259, 2011). "In light of renewed interest in targeting glucagon signalling for the prevention and treatment of hyperglycemia and diabetes, it is important to understand how absolute glucagon deficiency and impaired glucagon secretion affect energy homeostasis." (PMID 22046328, 2011). "Here, we demonstrate that in db/db mice α-cell number and plasma glucagon levels increased as diabetes progressed." (PMID 21283589, 2011). "Our study corroborates certain beneficial effects of reduced glucagon signalling, and supports its therapeutic potential in the prevention and treatment of diabetes and other metabolic-related diseases." (PMID 22046328, 2011). "As glucagon signaling plays important roles in type 2 diabetes pathogenesis, it is reasonable to experiment with inhibiting glucagon signaling in an attempt to improve diabetes control." (PMID 21853126, 2011). "Although glucagon signaling inhibition clearly shows various metabolic benefits for diabetes treatment in animal (mostly murine) models, hyperglucagonemia and α cell hyperplasia cast doubt on the safety of that approach." (PMID 21853126, 2011). "Although it was not unexpected to find lower levels of insulin in the diabetic beta cells, it was surprising to find decreased alpha cell glucagon, especially since one of the hallmarks of diabetes is inappropriately increased glucagon secretion." (PMID 20548773, 2010). "That is, as reviewed by Jiang and Zhang, the absolute levels of glucagon or the ratios of glucagon to insulin are often elevated in various forms of diabetes in both animal and human subjects." (PMID 19943948, 2009). "Based on the physiological fact that stress increases glucagon secretion through the HPA axis, it is reasonable to consider stress as one of the causes of hyperglycemia in diabetes." (PMID 19943948, 2009).
diabetes (continued). "Diabetes is generally considered as a peripheral disease characteristic of dysfunction of such peripheral glucose-insulin-glucagon (GIG) interactions." (PMID 19943948, 2009). "(For more information on diabetes and on alcohol’s effects on insulin, glucagon, and the management of diabetes, see the article by Emanuele and colleagues, pp." (PMID 15706790, 1998). "Using a rodent model of insulin-requiring diabetes, we evaluated the effects of daily SSTR2a administration with insulin dosing (study A: 8 days) and repeated exposures to hypoglycemia (study B: 4× over 11 days) on glucagon and glycemia." (PMID 41502124, 2026). "Additionally, in individuals with diabetes, glucagon secretion in response to hypoglycemia is diminished, indicating alpha cell dysfunction." (PMID 41575482, 2026). "Moreover, IDE is involved in the degradation and inactivation of amylin and glucagon, hormones, growth factors, neurotransmitters, and amyloid beta (Aβ), which implies its engagement in the modulation of diabetes-related cognitive impairment." (PMID 41301404, 2025). "Both animal and human studies have demonstrated that β-cells revert to a dedifferentiated stage during diabetes progression, losing their specialized functions and adopting progenitor-like or alternate endocrine phenotypes, including α-like glucagon-producing cells." (PMID 41473243, 2025). "In parallel, we plan to evaluate whether targeting the glucagon axis may offer protective or disease-modifying effects in models of diabetes-related organ damage." (PMID 40822953, 2025). "In the present study, we provide evidence that PDAC-associated diabetes is distinguished by a global downregulation of key islet hormones (INS, GCG) as well as β-cell-enriched transcription factors such as MAFA and PAX4, and hormone receptors such as GCGR, SSTR3 and SSTR5." (PMID 40244011, 2025). "This comprehensive regulation by glucagon highlights its critical function in maintaining metabolic homeostasis, making it a key target for therapeutic strategies in metabolic disorders such as diabetes, hyperlipidemia, and obesity." (PMID 39948335, 2025). "Transcriptomic data indicated significant downregulation of islet hormone genes insulin (INS) and glucagon (GCG) but not somatostatin (SST) in PDAC-associated diabetes, consistent with a type 3c diabetes phenotype." (PMID 40244011, 2025). "Diabetes-related information and glucagon knowledge data among participants." (PMID 40585626, 2025). "Somatostatin from pancreatic δ‐cells is a paracrine regulator of insulin and glucagon secretion, but the release kinetics and whether secretion is altered in diabetes is unclear." (PMID 39803760, 2025). "It has been shown that although glucagon has these effects, the glucose response to glucagon in individuals with insulin-treated diabetes is highly variable, influenced by the levels of insulin and the ratio of insulin to glucagon in the body, along with the timing of the most recent injection." (PMID 41510436, 2025). "By maintaining high-affinity binding and inducing prolonged activation of GLP-1R, dulaglutide effectively enhances insulin secretion, inhibits glucagon release, and delays gastric emptying—mechanisms critical for glycemic control in type 2 diabetes mellitus (T2DM)." (PMID 41226200, 2025). "Additionally, patients with diabetes diagnosed in the past five years were more aware of glucagon than those with diabetes for more than five years." (PMID 40585626, 2025). "Considering glucagon as a therapeutic target—even in conditions like diabetic ketoacidosis—could enhance treatment efficacy." (PMID 41149695, 2025). "Chronic alterations in glucagon secretion—commonly observed in patients with diabetes—may contribute to cardiovascular, renal, and hepatic dysfunction beyond glycemic control." (PMID 40822953, 2025). "Another hormone that is an important target for new drugs in diabetes and obesity is glucagon." (PMID 41178712, 2025).
diabetes (continued). "In T1DM this glucagon response is often impaired or absent, significantly increasing the risk of hypoglycaemia, particularly in children, individuals with long-standing diabetes where glucagon secretory capacity is impaired, or those with hypoglycaemia unawareness." (PMID 40718205, 2025). "In diabetes, insulin is either low (type 1 diabetes) or hypofunctional due to resistance (type 2 diabetes) and glucagon secretion is higher in both cases, thus resulting in an increased glucagon/insulin ratio in terms of their biological action." (PMID 40305364, 2025). "Therefore, diabetic patients should be educated about glucagon, especially those with a longer duration of diabetes." (PMID 40585626, 2025). "In diabetes, this leads to a new baseline glucagon level that is elevated." (PMID 39594662, 2024). "Future longitudinal studies are warranted to examine whether altered glucagon and GLP-1 secretion in children and adolescents with obesity and insulin resistance increase the risk of diabetes development into adulthood." (PMID 38087928, 2024). "Our findings therefore support speculations that there is a two-way connection between MASLD and diabetes and suggest that glucagon could be a main factor in the pathogenesis." (PMID 38705923, 2024). "Diabetes mellitus (DM) is a group of physiological disabilities characterized by hyperglycemia resulting from insulin resistance, insufficient insulin excretion, or elevated glucagon excretion." (PMID 39590327, 2024). "However, glucagon signalling has pleiotropic effects which are increasingly recognised, and its role in diabetes remains to be fully elucidated." (PMID 38677509, 2024). "Thus the therapeutic utility of glucagon has been mainly limited to its use as an emergency treatment for severe hypoglycemia in patients with diabetes." (PMID 38477666, 2024). "Additionally, expansion of α-cell mass, increased cell proliferation, and elevated plasma glucagon levels were reported in diabetes mellitus." (PMID 39337311, 2024). "The phase of glucagon secretion in diabetes after oral ingestion of glucose intake or a meal remains unclear, with only a few studies focusing on type 2 diabetes (T2D)." (PMID 39149119, 2024). "Indeed, glucagon antagonists have been proposed as potential anti-hyperglycaemic agents in type 2 diabetes mellitus." (PMID 39236784, 2024). "As diabetes progressed, pancreatic glucagon content was significantly reduced in diabetic mice." (PMID 38612880, 2024). "Our findings suggested that the adropin peptide may play a role in modulating glucagon secretion in an animal model of diabetes mellitus, offering a potential therapeutic target for this chronic disease." (PMID 39337311, 2024). "Some authors claim that in diabetes patients, the addition of glucagon inhibition to standard antihyperglycaemic therapy could be a useful complementary approach." (PMID 38579770, 2024). "In recent years glucagon has gained increasing interest in both obesity and diabetes research." (PMID 39027470, 2024). "Inhibition of this enzyme results in a reduction in glucagon and blood glucose levels, and may therefore be useful as an alternative treatment for diabetes." (PMID 38535452, 2024). "The resolution of postoperative complications such as diabetes observed in some patients after pancreatoduodenectomy may be explained in part by the decrease in glucagon and pancreatic polypeptide release measured." (PMID 39430095, 2024). "Many patients with diabetes have elevated levels of circulating glucagon." (PMID 38072640, 2024). "Animal-based protein intake exacerbates the rise in plasma glucagon in patients with diabetes." (PMID 38800782, 2024). "In addition, with regard to the clinical implications for diabetes treatment, it is worth noting that different dietary regimens have effects on glucagon release and action." (PMID 38681771, 2024).
diabetes (continued). "One major difference between the models of glucagon signalling deficiency and people with MASLD is that the former have improved glucose tolerance compared to controls, whereas people with MASLD have a high prevalence of pre-diabetes and type 2 diabetes." (PMID 38579751, 2024). "The aim of the study was to understand whether decreases in weight and IR or hormonal (insulin, glucagon, and incretin) changes lead to diabetes remission after bariatric surgery." (PMID 39598143, 2024). "Considering the common origin of the pancreas and gallbladder together with extrahepatic bile ducts, it is important to know if the porcine biliary tract has endocrine cells producing insulin and glucagon which can contribute to the pathophysiology and treatment of diabetes." (PMID 38094502, 2023). "Regarding glucagon, in addition to its known hyperglycemic effect, the hormone has demonstrated a number of systemic metabolic effects that make it of interest in the therapy of obesity and diabetes." (PMID 37729025, 2023). "Our finding regarding the ability of the biliary tract epithelium to produce extrapancreatic glucagon and insulin may contribute to improving the treatment of diabetes." (PMID 38094502, 2023). "There is a growing interest in the role of glucagon in type 2 diabetes mellitus (T2DM)." (PMID 37762748, 2023). "A better understanding of the molecular mechanisms governing glucagon secretion could have major implications for understanding abnormal responses to hypoglycemia in patients with diabetes and provide novel avenues for diabetes management." (PMID 37140984, 2023). "Another experimental indication is pumping glucagon parenterally and insulin to treat diabetes." (PMID 37629010, 2023). "Since the main pharmacological use of glucagon today is as a rescue treatment for severe hypoglycemia, especially in patients with diabetes mellitus, patients with VLCAD suffering from an acute metabolic crisis might also benefit from treatment with glucagon." (PMID 37512487, 2023). "Moreover, the diabetes-induced reduction of β-cells in islets of Langerhans is followed by the increased appearance of glucagon-positive α-cells migrating to the center of the islet." (PMID 37600723, 2023). "Here, we identified a negative association between islet RAGE and glucagon expression in the adolescents within the type 1 diabetes cohort, which was not seen in the absence of diabetes." (PMID 37558746, 2023). "Pancreatic tissue sections from 15 non-diabetic, eight double autoantibody-positive and ten type 1 diabetic (0–2 years of disease duration) organ donors were obtained from the Network for Pancreatic Organ Donors with Diabetes, and stained for insulin, glucagon, CD3 and CD8 by immunofluorescence." (PMID 36884056, 2023). "This review highlights the normal regulatory role of pancreatic somatostatin signaling in healthy islet function and how the inhibition of somatostatin receptor signaling in pancreatic α-cells may restore normal glucagon counterregulation in diabetes mellitus." (PMID 38298268, 2023). "Therefore, therapies that can restore normal α-cell function/glucagon secretion would significantly improve diabetes treatment, particularly for better prevention of hypoglycaemia." (PMID 37159865, 2023). "Diabetes occurs secondary to the direct effects of glucagon." (PMID 37628857, 2023). "Feeding zebrafish with 10% cholesterol and immersing them in a 2% glucose solution simultaneously for 19 days resulted in more symptoms of diabetes in zebrafish larvae, such as significant increases in insulin, glucagon, glucose, triglyceride, and cholesterol levels." (PMID 37569372, 2023). "However, animal studies have shown that hypothalamic glucagon signalling inhibits hepatic glucose production and suggested that hypothalamic glucagon resistance disrupts glucose homeostasis in diabetes and obesity." (PMID 36943057, 2023). "While insulin levels are low in diabetes, glucagon is present in excess." (PMID 37850072, 2023).